TRIM49D2 (tripartite motif containing 49D2)
Synonyms: TRIM49L; TRIM49L1; TRIM48L1; formerly TRIM49D2P
Gene: Protein-coding gene on chromosome 11 (89,924,064 to 89,933,063, forward strand). Ensembl gene ENSG00000233802.
Subcellular location (Human Protein Atlas): Nucleoplasm; Cytosol
Gene Ontology:
Molecular function: ubiquitin protein ligase activity; zinc ion binding
Biological process: innate immune response; regulation of gene expression
Cellular component: cytoplasm
Homologues: Paralogues in human: TRIM49D1 (100% identical), TRIM49B (85% identical), TRIM49C (85% identical), TRIM49 (85% identical), TRIM51 (74% identical), TRIM51G (70% identical), TRIM43 (51% identical), TRIM43B (50% identical), TRIM64 (44% identical), TRIM64B (44% identical), TRIM48 (44% identical), TRIM64C (43% identical), and 68 more.